FOXP3 (forkhead box P3)
Diseases named in the same sentence as FOXP3 in open-access papers (continued):
Sharing a sentence is not in itself a finding about the gene and the disease.
tumor (continued). "On the contrary, the existence of fractions of CTLs that express FOXP3 secrete immunosuppressive interleukin (IL)-10 and co-express molecules associated with anergy, exhaustion, or unresponsiveness in tumor-infiltrating lymphocytes was reported." (PMID 31016433, 2019). "This condition favors the development of an immunosuppressive environment by recruiting suppressor cells, like CD4+, CD25+, FOXp3+ Treg (regulatory T cells), myeloid-derived suppressor cells, tumor-associated macrophages, and regulatory dendritic cells." (PMID 30766448, 2019). "Tumor-associate macrophages, modified neutrophils, and Foxp3+ Tregs, are also recruited by the tumor to promote its progression." (PMID 31181772, 2019). "A recent report found that RUNX3 binds to the promoter of FOXP3 and increases Treg population in the tumor microenvironment, which is associated with the progression of breast tumors." (PMID 31075939, 2019). "Myeloid-derived suppressor cells (MDSCs), regulatory T-cells (Treg/CD4+CD25+FOXP3+), and tumor-associated macrophages (TAMs) are tumor-modified immune cells that hinder the clearance of cancer cells locally and even in distant organs." (PMID 31769418, 2019). "Studies have found that high infiltration of CD3+ cells in tumor epithelium and stroma suggest a better OS, while high infiltration of forkhead box P3 positive (FOXP3+) T cells in tumors was associated with poor prognosis." (PMID 30999966, 2019). "The metastatic tumour microenvironment contains increased numbers of suppressive T-regulatory cell markers (FoxP3+) that are also associated with tumour immune-resistance." (PMID 29440650, 2018). "In conclusion, we demonstrated that the excessive expression of FOXP3 in tumor-infiltrating CD4+ T cells of CRC patients is caused, at least in part, by the upregulation of STAT5 and TET2." (PMID 30013992, 2018). "These elevated levels of Foxp3+ T cells are consistent with tumor associated impairment of anti-tumor immunity in both groups." (PMID 30285905, 2018). "A high CD8+: FOXP3+ T cell ratio in the para-cortex (tumour-free) of metastatic ALNs was significantly associated with a pCR following NAC." (PMID 29390966, 2018). "Another study has shown a significant inverse association between the tumor PD-L1 expression and FOXP3+ cell density." (PMID 29854854, 2018). "In contrast, we have shown that NAC reduced both blood and tumour FOXP3+ T cells concurrently in patients with LLABCs and that high levels of FOXP3+ T cells in blood and tumour following NAC were associated with a poor pathological response." (PMID 29390966, 2018). "More importantly, reduction in tumor progression in Dox-treated animals was strongly associated with reduced CD4+Foxp3+ Treg cell infiltration within tumor tissue as well as in tumor-draining lymph nodes (dLN)." (PMID 30413714, 2018). "High levels of CD8+ T cells and low levels of FOXP3+ T cells in para-cortical areas (tumour-free) were associated with pCRs following NAC." (PMID 29390966, 2018). "Generally, while CD8+ T cell tumor infiltration is associated with favorable prognosis, a high prevalence of Foxp3+ Tregs within the tumor microenvironment indicates a malignant phenotype and adverse outcome for different kinds of cancer." (PMID 29499656, 2018). "We found that a higher density of FOXP3+ T cell tumor infiltration was associated with a worse survival." (PMID 30003113, 2018). "On the other hand, the expression of Foxp3 in tumor cells is associated with an increase in the secretion of sCTLA-4, which was recently reported to be a favorable predictor of clinical outcome in advanced cancers." (PMID 30460193, 2018). "The infiltrating FoxP3+ regulatory T cells (Tregs) in tumor tissues were associated with survival, while CD8+ tumor infiltrating lymphocytes (TILs) were not." (PMID 30359281, 2018). "Loss induces systemic autoimmunity and expansion of Foxp3+ Tregs (Treg-extrinsic mechanism).Mediates SDF1/CXCR4 axis at the tumor site (Treg-extrinsic mechanism)." (PMID 30364244, 2018).
tumor (continued). "In cutaneous T-cell lymphomas, programmed death-ligand 1 (PD-L1) was expressed by MDSCs as well as by tumor cells themselves and was associated with inhibition of T-cell proliferation and promotion of regulatory FoxP3+ T cells." (PMID 30101129, 2018). "Huh7, PLC and 7721 only expressed the full-length FOXP3, while other tumor cell lines also expressed the splice variants as observed in the T cells." (PMID 28903735, 2017). "Forkhead box protein 3 (FOXP3) is implicated in tumor progression and prognosis in various types of tumor cells." (PMID 29089565, 2017). "In the present study, FOXP3 g.10403A>G and g.8048A>C polymorphisms were analyzed in 117 BC patients and 300 neoplasia-free controls." (PMID 28713192, 2017). "CCL5 has been implicated in the recruitment of CD4 + CD25 + Foxp3+ Tregs, leading to the generation of a suppressive environment that supports tumor tolerance." (PMID 29216863, 2017). "In this same patient cohort, we recently demonstrated that a low density of Foxp3+ Tregs within the tumour stroma following neoadjuvant CRT was strongly associated with pCR." (PMID 28177891, 2017). "Accumulation of Foxp3+ T-regulatory (Treg) cells in the tumor microenvironment is associated with tumor immune evasion and poor patient outcome in the case of many solid tumors." (PMID 29236775, 2017). "Other study using immunohistochemistry technique also showed association of FOXP3 expression by tumor cells with higher histological grade." (PMID 28713192, 2017). "So far we have demonstrated that DTX‐mediated Treg depletion in tumor bearing BALB/c FoxP3.dtr mice is associated with significant increases in CD8 and CD4 T cell activation and an overall survival benefit, compared to untreated controls." (PMID 28250921, 2017). "In support of this, in vivo studies have shown that DTA-1 not only activates effector T cells and mediates depletion of tumor-infiltrated Tregs, but also results in the loss of FoxP3 expression." (PMID 28807056, 2017). "Coincidently, survival analysis revealed that patient with high level of FOXP3 in tumor cells was remarkably and independently associated with improved survival and reduced recurrence, regarding FOXP3 as an independent prognostic factor of HCC patient outcome." (PMID 28903735, 2017). "The identification of a Th17-to-exTh17 Foxp3+ transdifferentiation pathway in the development of tumour-associated Treg cells warrants new approaches in targeting Treg cell-associated immunosuppression." (PMID 28290453, 2017). "CD8+ T cell infiltration in AG and FoxP3+ regulatory T cells (Tregs) in the tumor invasive margin (TM) were also associated with improved OS (HR=0.90, 95% CI=0.83-0.97; HR=0.65, 95% CI=0.48-0.87, respectively)." (PMID 28977947, 2017). "Tregs would increase in tumor site or be induced into CD4+, CD25+ T cells by tumor-associated DCs (dendritic cells) and FOXP3 gene played a critical role in Tregs’ differentiation, development and maintenance of function during this process." (PMID 28029650, 2017). "In contrast, tumor-associated macrophages and Foxp3+ tumor-infiltrating lymphocytes correlated with favorable prognosis for NPC." (PMID 28715474, 2017). "Immunosuppressive FOXP3+ regulatory T cells (Treg) are known to accumulate within the tumour microenvironment in a variety of cancers and are associated with deficiencies in effector T cell responses and poorer outcomes." (PMID 28239749, 2017). "Previously, we and others have demonstrated that high-density of FOXP3+ Treg infiltration was associated with tumor aggressiveness and poor clinical outcome in HCC." (PMID 28903735, 2017). "More importantly, we found that TSA overcomes the tumor-associated immunosuppressive microenvironment by reducing the number of CD25+FoxP3+ regulatory T cells and myeloid-derived suppressor cells (MDSCs)." (PMID 28489607, 2017).
tumor (continued). "In summary, we demonstrated that FOXP3 was expressed in tumor cells and an increased expression of FOXP3 was associated with better survival and reduced recurrence." (PMID 28903735, 2017). "FOXP3 reduced tumor growth and invasion in vitro and in vivo, however, the splice variant of FOXP3 led to impaired protective function." (PMID 28903735, 2017). "We observed a significantly lower CD8+/FOXP3+ ratio in patients with tumours containing activating mutations of the Wnt pathway compared with wild-type tumours (2.65 ± 1.2 versus 6.08 ± 5.0, P = 0.043, Mann–Whitney U test)." (PMID 28961847, 2017). "This information tempted us to look in-depth to the molecular mechanism associated with the maintenance of FOXP3 expression in tumor-CD8+ Treg cells." (PMID 28487507, 2017). "With the data of our cell and animal models, we found that Δ3,4-FOXP3 showed a moderate inhibition on tumor growth and migration than full-length FOXP3, indicating a restricted tumor-suppressive function probably caused by exon loss." (PMID 28903735, 2017). "STAT3 regulates tumor-associated inflammation, and its activation downregulates the Th1 response by upregulating Foxp3+ Treg cells." (PMID 29051427, 2016). "On the other hand, the presence of the Th2 marker FOXP3+ in the tumor has been associated with worse prognosis." (PMID 27777769, 2016). "Intra-tumoral accumulation of FoxP3+ Tregs is associated with increased tumor vasculature density in endometrial cancers." (PMID 27509527, 2016). "Tumor-infiltrating FoxP3+CD25+CD4+ regulatory T (Treg) cells can promote local tumor growth through exerting immunosuppressive activities against tumor-associated antigen (TAA) T cell responses." (PMID 27177223, 2016). "This protective effect was associated with significant reduction in tumor-infiltrating FoxP3+ and IL-10+ Treg cells, and a corresponding increase in tumor-infiltrating CD4+ and CD8+ T cells that secreted IFN-γ." (PMID 26941742, 2016). "While FOXP3 gene expression levels in the tumor were significantly associated with better outcomes, the presence of FOXP3+ cells in the stroma had the opposite effect." (PMID 27463005, 2016). "There was a significant association of T lymphocyte subsets (CD4+, CD8+, and FOXP3+) with tumour grade: infiltration by CD4+ and CD8+ T cells, intratumoural (p = 0.026 and p = 0.038, resp)." (PMID 27777963, 2016). "In term of disease progression, univariate analyses demonstrated that tumor stage, intravesical therapy, and Foxp3 expression were significantly associated with PFS." (PMID 27557492, 2016). "Immunoprofiling of early pulmonary lesions indicated that autophagy inactivation did not alter the global infiltration of the CD3ε+ T cells, but the amount of infiltrating Foxp3+ regulatory T cells (Tregs), which was increased in autophagy-deficient tumor." (PMID 27917371, 2016). "In some cancers (colorectal, ovarian, bladder, head, and neck) high levels of tumour-infiltrating FOXP3+ T cells were found to be associated with an improved prognosis." (PMID 27777963, 2016). "STAT3 regulation of inflammation during M. tuberculosis infection differs from tumor-associated inflammation by downregulating Foxp3+ Treg cells and macrophage inflammatory response and modulating Th cell response." (PMID 29051427, 2016). "Forkhead box protein p3 (Foxp3) is crucial to the development and suppressor function of regulatory T cells (Tregs) that have a significant role in tumor-associated immune suppression." (PMID 27284967, 2016). "For example, this method allows for the assessment of FOXP3+ regulatory T cells (Tregs) in tumor tissues, which have been shown to be associated with adverse prognosis." (PMID 26885371, 2016). "The presence of CD8+ cells in the tumor compartment was associated with better outcome, whereas the presence of FOXP3+ cells was associated with worse overall survival." (PMID 27463005, 2016).
tumor (continued). "Collectively, our data indicate that Nrp-1 deficiency in CD4+Foxp3+ regulatory T cells in combination with increased Th1 and Th17 cell immunity results in decreased tumor growth, although elevated expression of Tregs is detected in IL-10−/− B16/F10 mice." (PMID 27075020, 2016). "FOXP3+ Tregs, part of tumor-infiltrating lymphocytes (TILs), play a critical role in immune tolerance and deficiency of anti-tumor immunity." (PMID 27566250, 2016). "Notwithstanding, AA homozygous samples for rs3761548 and rs2232365 of FOXP3 polymorphisms, considered variant and ancestral genotypes, respectively, presented larger tumor size (>8 cm)." (PMID 27830498, 2016). "The presence of Foxp3 expression in cancer cells has been proved to be associated with tumor biological behaviors regulation." (PMID 27457382, 2016). "Increased tumor IL-10+ Breg frequency was also associated with increased FoxP3+ Treg infiltration and reduced survival." (PMID 27437104, 2016). "Treg cell proliferation is known to be significantly associated with tumor invasion and poor prognosis, and increased proportions of Foxp3+ Treg cells were shown to be an important predictor for the high recurrence and poor survival rates of HCC patients." (PMID 27439521, 2016). "High ratios of CD8+ to Foxp3+ T-cells among TILs, for example, have been shown in a variety of solid tumors to be associated with favorable tumor characteristics, response to therapy and radiation, and improved patient survival." (PMID 26317902, 2015). "We found that an increased percentage of tumor occupied by CD45+ cells was strongly associated with an enhanced tumor-infiltration by Tbet+ cells and Foxp3+ cells." (PMID 26357849, 2015). "In the present study, high-grade tumor budding was associated with increased counts of peritumoral FOXP3+T-cells." (PMID 25669968, 2015). "The presence of high tumor stroma infiltrating Foxp3 + CD4+ T cells was independently associated with improved NSCLC patients overall survival (P < 0.05)." (PMID 26604855, 2015). "Our study demonstrated that tumor infiltrating Foxp3 + CD4+ T cells are associated with improved NSCLC patients' survival." (PMID 26604855, 2015). "High FOXP3+ tumor infiltrated lymphocyte levels were strongly associated with prolonged recurrence-free survival among TNBC patients but not ER-negative cases." (PMID 26462021, 2015). "We found that tumors that are high in both CD4+ and Foxp3+ T-cell content were associated with significantly higher average tumor PD-L1 expression (p = 0.014)." (PMID 26317902, 2015). "γδ-T cells show positive correlations with CD4+ FOXP3+ T cells, and are associated with poor outcomes and advanced tumor stage, as well as low disease-free and overall survival in patients with breast cancer." (PMID 26300242, 2015). "A high level of Foxp3+CD4+ T cells infiltration in the tumor stroma was found to be independently associated with the better overall survival (Exp(B), 3.69; 95 % CI of Exp(B), 1.05–12.96; P = 0.041)." (PMID 26604855, 2015). "Contrasted with the possible tumor-promoting role of these cells in the progression of established tumors, the role of Foxp3+CD4+ T cells in initial tumor transformation caused by chronic inflammation remains elusive." (PMID 26604855, 2015). "The results from the ongoing Phase Ia/Ib clinical trial (NCT01494688) indicate that RG7155 treatment is well tolerated and effectively depletes macrophages associated with a tumor, which results in a decreased number of FOXP3 positive Treg lymphocytes." (PMID 26077607, 2015). "Increased numbers of FoxP3+ cells are associated with tumor infiltration of FoxP3+ cells, thus implying a benchmark number of Treg cells necessary for invasion into the tumor tissue (p = 0.001)." (PMID 25365237, 2014). "Tumor-associated Tregs express the IL-23 receptor, which activates Stat3, resulting in the upregulation of the Treg-specific transcription factor Foxp3 and the immunosuppressive cytokine IL-10." (PMID 24586528, 2014).
tumor (continued). "To further characterize the M2 macrophages infiltrating IK tumors in our tumor model, we investigated the expression of several markers associated with immunosuppression including Foxp3." (PMID 25264896, 2014). "Our work indicates that in the absence of OX40 and CD30, FoxP3-dependent Tregs are dispensable, and mice deficient in OX40, CD30, and FoxP3 mount excellent CD8-dependent anti-tumor immune responses." (PMID 24782861, 2014). "A high density of tumor infiltrating Foxp3+ cells has shown to be associated with an unfavorable prognosis in a wide range of human carcinomas." (PMID 24997850, 2014). "In accordance with previous findings suggesting an immunosuppressive role of FoxP3 in PDAC cells, high FoxP3 expression in tumor cells was associated with a low number of CD4+ T cells but elevated numbers of regulatory T cells as detected by FoxP3+ T cells." (PMID 24797069, 2014). "Abundance tumor-infiltrating FoxP3+ T cells are expected to be associated with an unfavorable prognosis, as expected from their capacity to inhibit antitumor immunity." (PMID 24827118, 2014). "Relatively low levels of CD8+ effector cells in comparison to FoxP3+ Treg cells are significantly associated with lower histological tumor grading (p = 0.001)." (PMID 25365237, 2014). "Using multiple assays, our observations indicate that Foxp3 can be expressed in tumor-associated macrophages." (PMID 25264896, 2014). "In PDAC, tumor related FoxP3 expression was associated with an immunosuppressive function in vitro but an analysis regarding its impact on PDAC progression is still pending." (PMID 24797069, 2014). "iii) Low numbers of CD4+ (C) but high numbers of FoxP3+ (CD4+) T cells (F) were associated with high FoxP3 expression in tumor cells (O1)." (PMID 24797069, 2014). "The authors point out that, overall, the associations between FOXP3 expressions in tumor cells are with poor patient's prognosis." (PMID 24877082, 2014). "In this study, by combining the immune-related tumor markers HLA class I, HLA-G and Foxp3+, we reported an independent association between tumor immune-phenotype and patient outcome." (PMID 24997850, 2014). "We found that FoxP3+ cells located within lymphoid aggregates surrounding the tumor were strongly associated with reduced survival time (P = 0.007)." (PMID 25365237, 2014). "Addressing the issue of Foxp3 stability within tumor-associated Treg cells, a recent report evaluated tumor-resident Treg cells." (PMID 23874336, 2013). "In these patients, with different tumor stages, a better prognosis and an increased overall survival were associated with higher infiltration of FOXP3+ T cells compared to patients with a poor tumor outcome." (PMID 23986759, 2013). "Inversely, borderline significance was observed between the association of tumor-cell cytoplasmic FOXP3 expression and poor OS (HR: 2.47; 95% CI: 0.94–6.50; P=0.058)." (PMID 24649219, 2013). "FOXP3+ Tregs are immunosuppressive, therefore, their abundance in tumor infiltrates is associated with an unfavorable clinical outcome." (PMID 24649219, 2013). "Kaplan-Meier curves confirmed that FOXP3 expression localized in the cytoplasm or nucleus of tumor cells was associated with worse (log-rank test, P=0.058) or improved (log-rank test, P=0.016) OS, respectively." (PMID 24649219, 2013). "The presence of tumor cell-conditioned medium also causes conventional CD4+ T cells to transiently upregulate the expression of Foxp3 and TGF-β." (PMID 23720663, 2013). "Univariate and multivariate analysis demonstrated that the locoregional control of the tumor was positively associated with CD4+FOXP3+ regulatory cell infiltration." (PMID 23986759, 2013). "The EOC-specific recruitment of CD4+CD25+FoxP3+ regulatory T-cells (Treg), tolerogenic dendritic cells (DC), B7-H4+ tumor-associated macrophages (TAM) and myeloid-derived suppressor cells (MDSC) fosters immune privilege and predicts reduced survival in EOC." (PMID 23763830, 2013).